IL6 (interleukin 6)
Diseases named in the same sentence as IL6 in open-access papers (continued):
Sharing a sentence is not in itself a finding about the gene and the disease.
asthma (continued). "Therefore, results obtained with Mlys-IL-6 KO mice, defined the contribution of IL-6 produced by macrophages in pathogenesis of acute HDM-induced asthma." (PMID 30534125, 2018). "In the present study, we demonstrated that tiotropium bromide improved bronchoconstriction, and that it significantly reduced the concentrations of IL-5, IL-6, IL-13, and KC/CXCL1 in BALF, and subsequently led to reduced neutrophilic airway inflammation in a mouse model of OVA-induced asthma." (PMID 29882826, 2018). "When comparing the effectiveness of the two periodontal treatments in the mice without asthma, we noticed that the conventional treatment decreased the macrophages, as well as IL-6 and TNF-α, corroborating with the literature." (PMID 29145431, 2017). "In the present study, LIF, and to a lesser degree IL-6, expression was increased in asthmatic vs non-asthmatic children, with a further increase in uncontrolled asthma vs controlled asthma." (PMID 28493984, 2017). "Enhanced thrombin generation is driven in asthma by a systemic inflammatory state mediated by IL-6 and to a lesser extent TNFα, however, not periostin." (PMID 28429138, 2017). "Comparatively similar levels were recorded for nine out of the 10 cytokines measured [e.g., – Interleukin (IL)-1β, IL-6, IL-10], regardless of study participant asthma status." (PMID 28424616, 2017). "In addition, markers of systemic inflammation (IL-6, CRP, alfa-dimer, and fibrinogen) were the highest in patients with permanent asthma even though patients were using modern controller asthma medication." (PMID 27212806, 2016). "Therefore, the aim of the study was to assess the amount and activity of MMP-9 in context of pro-inflammatory cytokines (IL-6, IL-8 and tumor necrosis factor, TNF), measured in EBC of asthma-suffering children, treated with inhaled steroids." (PMID 25650123, 2015). "Similar to the results reported for proliferation, cells from patients with severe and nonsevere asthma had a reduced sensitivity to JQ1+ with a significant repression of IL-6 release observed at 100–1000 nm of JQ1+ (p < 0.001)." (PMID 25697361, 2015). "IL-2, IL-4, IL-6, IL-17a and TNF-α were reported to be involved in asthma." (PMID 24735374, 2014). "Using several bioinformatics tools, we predicted that these microRNAs may play a role in airway inflammation and remodelling by targeting multiple mRNAs and affecting inflammatory mediators important in asthma such as TGF-β, IFNs, IL-6 and IL-8." (PMID 25360780, 2014). "We present evidence that current smokers with asthma have increased sputum supernatant concentrations of IL6, 7 and 12 and an absence of sputum neutrophilia." (PMID 23951170, 2013). "Our results demonstrate that IL6 is elevated in both current and ex-smokers with asthma and this cytokine also failed to respond to oral dexamethasone." (PMID 23951170, 2013). "In severe asthma, Rorγt expression was significantly correlated with Il6 expression, but not in mild asthma." (PMID 23781124, 2013). "Homozygous carriers of HLX1 SNP rs3806325, which was previously associated with an enhanced risk for asthma, especially non-atopic asthma in childhood, showed increased levels of IL-13 (TH2) and additionally enhanced IL-6 secretion in this cord blood study." (PMID 22303482, 2012). "ASM cells from people with and without asthma were stimulated with TGFβ1 (1 ng/ml) with or without budesonide (10−8 M) and formoterol (10−10 and 10−8 M), and fibronectin expression and IL-6 release were measured by ELISA." (PMID 22500185, 2012). "None of the well-defined asthma/inflammatory genes (Il1b, Il4, Il10, Il13, Il6, Tnfa, Infg, Tgfb1) are differentially expressed, although they connect many of the genes that are." (PMID 18087596, 2007). "Indirect involvement of IL6 in the etiology of environmentally induced atopy and development of asthma can therefore not be excluded." (PMID 16759385, 2006).
asthma (continued). "The presence of IL-6 in the airways of individuals with asthma may not solely stem from ongoing inflammation but rather from the "activated" state of pulmonary epithelial cells." (PMID 40292266, 2025). "However, few studies have investigated serum IL-6 concentration in children and adolescents with asthma, and none have examined the relationship between serum IL-6 levels and respiratory parameters." (PMID 40696834, 2025). "Fructus Xanthii exerts anti-asthmatic effects by modulating HSP90AB1/IL6/TNF and PI3K-AKT pathways, regulating inflammation, cell cycle, apoptosis, and immune homeostasis, providing empirical support for multi-target traditional Chinese medicine strategies in asthma management." (PMID 41403444, 2025). "However, to the best of authors' knowledge there are no studies demonstrating a clinical relevant reduction of IL-6 serum levels after anti-IgE treatment in patients with asthma." (PMID 40823190, 2025). "Subsequent exploration demonstrated a significant increase in Th2 cell population in the lungs of Cc10−/− mouse asthma model, indicating that CC10 might regulate Th2 cell differentiation and immune responses by suppressing IL-6 and TNF-α secretion from lung DCs." (PMID 39078462, 2024). "Asthmatic mice with and without fluconazole exhibited retardation of weight gain, increased IgE and IL-4 in serum, increased serum IL-6 but not serum TNF-α (increased serum IL-10 only in asthma with fluconazole), and prominent IL-4 and IgE in the lung homogenates." (PMID 39484217, 2024). "Additional research has demonstrated that IL-1β, IL-6, anti-IFN-γ, and IL-21, which is a cytokine environment that stimulates T cells in asthma to differentiate into the same biphenotypic cells, promote dual-positive TH2/TH17 cell differentiation, worsening asthma." (PMID 39439788, 2024). "Notably, an increase of immune cells was observed in the lungs of asthma mice, which may contribute to the elevated levels of TNF-α and IL-6 in the lung tissue." (PMID 39484217, 2024). "Similarly, in a study involving patients with asthma, the administration of nemiralisib did not yield statistically significant reductions in sputum IL-5, IL-13, IL-6 or IL-8 compared to placebo." (PMID 39427187, 2024). "Thus, IL-6 levels can be used as an auxiliary indicator to distinguish individuals with asthma from healthy non-asthmatic controls." (PMID 37173781, 2023). "Although previous efforts attempted to target the IL-6 pathway in asthma, none targeted sIL-6Rα." (PMID 38062491, 2023). "Many MCs mediators (PGD2, leukotriene C4 LTC4, IL-6, IL-13, TNF-α, tryptase, and chymase) interact with the epithelium, leading, altogether, to mucus hypersecretion by hyperplastic submucosal glands and epithelial goblet cells, which is a known key feature, especially in severe asthma." (PMID 37298721, 2023). "Finally, we obtained a total of eleven relevant studies on IL-6, which consist of 1977 patients with asthma and 1591 healthy non-asthmatic controls." (PMID 37173781, 2023). "Notably, adipokines may serve as a link between obesity and asthma, such as leptin, TNF-α, and IL-6." (PMID 36051916, 2022). "Moreover, the excessive synthesis by the adipose tissue of pro-inflammatory cytokines, such as IL-1β, IL-6, TNF-α, and TGF-β, may contribute to asthma pathogenesis." (PMID 35807067, 2022). "However, the siRNA-mediated knockdown of Ob-R receptors in these cells suppresses the leptin-mediated upregulation of IL-6, CCL11, and IP-10, indicating that leptin can play a detrimental role in promoting inflammation in asthma patients by stimulating fibroblast differentiation." (PMID 35888038, 2022).
asthma (continued). "Endotype, sex, age, asthma history, LM score, GOS score, sinus dominance, olfactory CT score, tissue eosinophilia, HNE subepithelial count, HNE perivascular count, serum eosinophil, IL5, IL6, INFγ, TNFɑ, and IL10 saw significant differences between the two groups." (PMID 36428479, 2022). "Nevertheless, IL6 has not been studied as a biomarker in childhood asthma." (PMID 36140412, 2022). "The expression of miRNA-221-5p was increased in model of asthma, compared with negative group The vitro model of asthma treated with miRNA-221-5p mimic resulted in the reduction of IL-6, IL-17, IL-21 and IL-22 levels, and induction of IL-10, IL-35 and TGF-β levels." (PMID 34863307, 2021). "Thus, IL-6 and STAT3 may have important roles in an OVA- and ozone-induced corticosteroid-resistant asthma model." (PMID 34760922, 2021). "The IL-6/STAT3 pathway may contribute to corticosteroid insensitivity in OVA + ozone–induced neutrophilic airway inflammation through regulation of Th17 cells and could provide new targets for individual treatment of corticosteroid resistance in asthma." (PMID 34760922, 2021). "However, 62% of obese patients had normal plasma IL-6, an observation that prompted the authors to examine the relationship between IL-6 inflammation, metabolic dysfunction, and asthma severity in obese and non-obese patients." (PMID 33418879, 2021). "The Th17/neutrophilic endotype of asthma in smokers, ACO and obese patients might be exacerbated by the systemic inflammatory response of SARS-CoV-2 infection, which is similarly driven by Th1-related cytokines, including IFNγ, IL-6, MCP1, IP10, and IL-1β." (PMID 34261543, 2021). "However, the regulation of the relationship between IL-6 and ferroptosis in asthma has not been reported so far." (PMID 34402724, 2021). "Subsequently, the OVA-induced asthma mice were treated with M2Φ-Exos, and we found a significant inhibition in fibrosis and cell apoptosis in mouse lung tissues, a reduction in the number of granulocytes, and a decline in the secretion of OVA-induced IL-1β, IL-6, TNF-α, and MCP-1." (PMID 33994863, 2021). "It was shown that IL-6 may shift differentiation of macrophages towards alternatively activated macrophages (M2), which play a key role in eosinophilic inflammation in HDM-induced asthma." (PMID 34084159, 2021). "However, at present, IL-6 McAb has not been widely used in the clinical treatment of asthma, and more clinical studies need to be reported." (PMID 34402724, 2021). "Interestingly, TSLP expression in moDCs from triple co-culture correlated positively with IL12p40, IL-6, and TNF-α in asthma, whereas in COPD with CHI3L1, IL12p40, IL-6, IL-8, TNF-α, and IL-1β suggesting a different pathway of immune response in asthma and COPD." (PMID 32842623, 2020). "To determine the cell type that makes the most significant contribution to the production of IL-6 during asthma, we first examined whether the lymphoid or non-lymphoid cells produce higher amounts of IL-6 in steady state and in response to HDM." (PMID 30534125, 2018). "However, recent studies provide evidence that IL-6, rather than being critically involved in lung inflammation, is actually playing a key role in the pathogenesis of asthma." (PMID 30534125, 2018). "Similar to our previous study showing that bvPLA2 was effective in decreasing Th2 cytokine expression in an asthma mouse model, treatment of WT mice with bvPLA2 following DFE/DNCB exposure significantly decreased the expression of Th1 and Th2 cytokines including IFN-γ, IL-4, IL-6, and IL-10." (PMID 29614845, 2018). "The suppressive effects of NS on IL-6 release from SEB-treated T lymphocytes may also be beneficial in the context of asthma as IL-6 is considered as a pro-inflammatory mediator and found at high levels in the serum of patients with asthma." (PMID 30333747, 2018). "CD4+ T-cells may, therefore, contribute to the development and progression of asthma by providing sIL-6R to cells initially non-responsive to IL-6." (PMID 30534125, 2018).
asthma (continued). "However, there are inconsistencies between studies regarding AEC IL-6 release, which is not increased in many children with asthma vs controls." (PMID 28493984, 2017). "Interestingly, studies have shown that infection with RSV also results in a significant increase in proinflammatory cytokines such as interleukin (IL)-1, IL-6, IL-8, interferon (IFN)-γ, and tumor necrosis factor (TNF)-α, contributing to development of recurrent wheezing or asthma." (PMID 29246125, 2017). "Our study was only powered to find an odds ratio of greater than 1.075, so if enhanced IL-6 trans-signaling does contribute to the pathogenesis of COPD, it is likely that this relationship is weaker than that observed for asthma in previous studies and may therefore be of limited clinical relevance." (PMID 28334838, 2017). "Our data demonstrated that reinfected mice showed an increased production of IL-17A, IL-6, TNF-α, IL-4 and IL-5, suggesting a pattern of mixed Th2/Th17 responsiveness, which was previously observed in studies with helminths and also allergic disorders, such as rhinitis and asthma." (PMID 26814713, 2016). "Furthermore, the inhibition of miR-221 but not miR-222 suppresses a release of IL6 in patients with severe asthma." (PMID 26891296, 2016). "Airway epithelial cells, which can release proinflammatory cytokines, such as IL-6 and IL-8, via autocrine and paracrine mechanisms, may accelerate the development and progression of asthma under the actions of both immunologic and nonimmunologic stimuli." (PMID 28116315, 2016). "However, sputum NGAL, YKL-40, and IL-6 were significantly elevated in ACOS and could differentiate ACOS from asthma and COPD, and further independently with reduced lung function in the multivariate stepwise analysis." (PMID 26673104, 2015). "We found that the deficiency in Gpr97 did not affect the altering obviously in Th2-related cytokines, including IL-4 and IL-6, and the significant decrease in the Th1-related cytokine IFN-γ, suggesting that Gpr97 is not essential for T cell proliferation and differentiation in asthma." (PMID 26132811, 2015). "A comparison of salivary marker concentrations between adults with and without asthma shows that IL-5, IL-6, MCP-1, and VEGF concentrations were present in statistically significantly higher concentrations in saliva collected from asthmatics compared to controls, and the other markers were not." (PMID 24409298, 2014). "Some of these cytokines namely IL-6, IL-8 (the human equivalent of murine KC) and MCP-1 have been previously shown to be up-regulated by PAR1 activation or down-regulated by PAR1 inhibition in non-infected human respiratory epithelial cells in models of asthma and idiopathic pulmonary fibrosis." (PMID 24015257, 2013). "The present study aimed to investigate the suPAR, CRP and IL-6 levels in asthma (asthmatic non-pregnant, ANP; N = 38; female N = 27) and asthmatic pregnancy (AP; N = 15), compared to healthy non-pregnant controls (HNP; N = 29; female N = 19) and to healthy pregnant women (HP; N = 58)." (PMID 23565268, 2013). "The asthmatic exacerbation resulted in increased serum levels of IL-6, soluble intercellular adhesion molecule-1 (sICAM)-1 and ECP, and increased concentrations of urinary leukotriene E4 (LTE4) and plasma histamine compared with patients with stable asthma and with the 30 control subjects." (PMID 22966430, 2012). "Availability of the non-essential amino acid arginine in the inflamed airway mucosa of patients with asthma is reduced markedly, but it is not known whether this can also lead to an exaggerated production of IL-6 and IL-8." (PMID 19575800, 2009). "Interestingly, in a subset of patients with high IL-6, significant T2 inflammation was not identified in the airway epithelium, suggesting a possible link between IL-6 trans-signaling (through sIL-6R) and non-T2 asthma." (PMID 39714726, 2025).
asthma (continued). "Other clinical trials on targeted IL-6 interventions for asthma are not currently well underway, and a phase 2a study evaluating the impact of Sirukumab in subjects with poorly controlled severe asthma was terminated in early may due to safety concerns (NCT02794519)." (PMID 37377958, 2023). "Finally, IL-6 was undetectable in 19/28 obese children with no asthma (67.8%), in 16/28 obese asthmatic children (57.1%) and in 28/28 children (100%) with normal-weight and asthma." (PMID 36291398, 2022). "The animal experiments verified that Danlong Dingchuan Decoction could effectively reduce IL-4, IL-6, IL-8, and IL-1β expression in the lung tissue of asthmatic mice, decrease TLR4 mRNA expression, and inhibit Th2 cytokine-mediated inflammatory response to treat asthma." (PMID 35186104, 2022). "Consequently, IL-17, IL-22, and IL-6, rather than Th2 cytokines, may be clinically relevant in obese patients with severe asthma." (PMID 36078171, 2022). "Thus, TNF neutralization may have a marked potential to improve lung functions, but demonstrates serious side effects, while blocking of IL-6 does not provide significant therapeutic effect in severe asthma." (PMID 34084159, 2021). "Rather than focusing on anti-IL6 agents to control the IL6 pathway (or other cytokines) as a therapeutic approach for asthma and other disease as it has recently been proposed, a valid novel approach could therefore be to consider the reported DEmiRs as potential therapeutic targets." (PMID 29231896, 2017). "Interestingly, when examining broncoalveolar lavage of children with asthma, while markers such as IL-13 and IL-6 can differentiate asthmatics from controls, and other cytokines can distinguish moderate from severe asthma, severe asthma itself does not have a clearly TH1 or TH2 inflammatory pattern." (PMID 27980705, 2016). "The levels of IL-4 and IL-6 and mast cell invasion were not altered in the Gpr97-/- asthmatic mice, indicating that Gpr97 might not take part in mast cell activation following IgE stimulation or cytokine production in the process of asthma induction." (PMID 26132811, 2015). "In our study, the functional role of the network may explain the increased secretion of important inflammatory cytokines in asthma, such as IL-6 or IL-8, while the individual microRNAs do not seem to be involved in any of the potentially pathological pathways tested (remodelling or inflammation)." (PMID 25360780, 2014). "We reasoned that although ORMDL3 levels may not affect the production of IL-6 or IL-8 cytokines, perhaps they were impacting gene expression of other important immune genes, such as IL-33, IL-25 and TSLP, which have all been implicated in asthma pathogenesis." (PMID 23369242, 2013). "Bronchoalveolar lavage samples from corticosteroid resistant non-smokers with asthma have also demonstrated increased concentrations of IL-6 and therefore IL-6 may be promoting corticosteroid resistant inflammation via promotion of Th17 development and activation." (PMID 23951170, 2013). "High IL-6 non-lean patients with asthma had a statistically lower lung function (both FEV1 and FVC) compared to low IL-6 non-lean patients with asthma (p < 0.001)." (PMID 39714726, 2025). "Down-regulation of miRNA-221-5p increased the levels of IL-6, IL-17, IL-21 and IL-22, and reduced those of IL-10, IL-35 and TGF-β in in vitro model of asthma, compared with negative group." (PMID 34863307, 2021). "Increased levels of IL-6 have also been found in serum of asthmatic patients and in BALF from patients with nonallergic asthma compared with that from patients with allergic asthma." (PMID 34639020, 2021). "A higher concentration of both JQ1/SGCBD01 and I-BET762 was needed to inhibit proliferation and IL-6 and CXCL8 release from cells from patients with asthma compared with nonasthmatic subjects." (PMID 25697361, 2015).